VDR (vitamin D receptor)
Diseases named in the same sentence as VDR in open-access papers (continued):
Sharing a sentence is not in itself a finding about the gene and the disease.
diabetic nephropathy (continued). "Activation of VDR may aid in the restoration of mitochondrial function in renal tubular epithelial cells under diabetic nephropathy conditions." (PMID 40620673, 2025). "The study found that VDR expression was reduced in both diabetic nephropathy mouse models and renal ischemia-reperfusion rat models, and the administration of VDR activators could alleviate renal ischemia-reperfusion injury in rats." (PMID 40243616, 2025). "Similarly, Chokhandre and his colleagues have shown that VDR activation by paricalcitol decreases renal inflammation and podocyte apoptosis in diabetic nephropathy models." (PMID 33294462, 2020). "Thus, the anti-proteinuric efficacy of vitamin D in diabetic kidney disease is mediated by vitamin D receptor activation." (PMID 28197449, 2014). "Taken together, this evidence suggests that 25OHD, 1,25OHD, and VDR may play a role in exacerbation of diabetic nephropathy, at least in part." (PMID 23226566, 2012). "The findings are consistent with the results of gene set enrichment analysis (GSEA), indicating that DDIT4 may modulate cellular oxidative stress levels through involvement in the VDR/mTOR/p70s6k/4E-BP1 signaling pathway, thereby ameliorating pathological damage associated with diabetic nephropathy." (PMID 38567351, 2024). "Vitamin D receptor (VDR), a member of the nuclear receptor superfamily, is an important anti-inflammatory mediator that has been studied widely in the pathogenesis of diabetic kidney disease." (PMID 30246029, 2018). "And transcription factors HIF1α, KLF4, KLF5, RUNX1, SP1, VDR, WT1 may be also related to diabetic nephropathy." (PMID 34735495, 2021). "Transcription factors HIF1α, KLF4, KLF5, RUNX1, SP1, VDR and WT1 may be related to diabetic nephropathy." (PMID 34735495, 2021). "Accumulating evidence indicates that vitamin D receptor (VDR) activation lowers unfavorable RAS activity; however, more human intervention studies evaluating whether this mechanism could influence diabetic kidney disease are needed." (PMID 23971740, 2013).
leukemia (30 papers, 2010 to 2026). A malignant (clonal) hematologic disorder, involving hematopoietic stem cells and characterized by the presence of primitive or atypical myeloid or lymphoid cells in the bone marrow and the blood. "It has been known for approximately thirty years that LCA, a weak VDR agonist, can cause G1/G0 cell cycle arrest in the human promyelocytic leukaemia cel line, HL60." (PMID 39796220, 2025). "VDR expression and activity have been documented to be associated with several types of leukemia, such as acute lymphoblastic leukemia (ALL) and acute myelocytic leukemia (AML)." (PMID 37880985, 2024). "More studies are needed to determine a possible association between VDR levels and the risk of leukemia development and/or disease prognosis." (PMID 32357551, 2020). "Furthermore, VDR deficiency led to a lower frequency of leukemia stem cells (LSCs; GFP+Lin−Sca-1+c-Kit+) in BM." (PMID 37880985, 2024). "The study aimed to determine whether polymorphism of VDR is responsible for the sensitivity of human leukemia and lymphoma cells to calcitriol and tacalcitol." (PMID 35053549, 2022). "Analysis of human leukemia and lymphoma cells selected for testing showed that calcitriol and tacalcitol sensitive MV-4-11, Thp-1 and HL-60 cells had a single nucleotide polymorphism at the initiation site of the VDR gene translation." (PMID 35053549, 2022). "However, more recent findings indicate that instead, or additionally, VDR polymorphisms could play a role in the differential responses of tumor cells to calcitriol, as observed in human leukemia and lymphoma lines." (PMID 37958423, 2023). "Importantly, we first showed that sensitivity to calcitriol and tacalcitol in leukemias and lymphomas could be determined by the VDR polymorphism." (PMID 35053549, 2022). "Previously 1,24,25(OH)3D3 was shown to stimulate HL-60 cells (a human leukemia cell line) to differentiate with a comparable potency to 1,25(OH)2D3 despite showing a 2 to 3-fold lower affinity for the chick intestinal VDR." (PMID 39456696, 2024). "In our study, we examined the role of VDR in leukemia and lymphoma patients with a focus on the impact of the SNPs ApaI, Tru9I, and FokI in the VDR gene." (PMID 38125732, 2024). "After constructing prognostic gene models in leukemia, we found that CD4, VDR and LST1 were the most significant prognostic risk genes." (PMID 37736548, 2023). "Subsequently, the levels of the VDR and 1,25D3-MARRS proteins of calcitriol and tacalcitol binding receptors and the VDR receptor polymorphism in human leukemia and lymphoma cells were ascertained." (PMID 35053549, 2022). "Very recently, we have demonstrated that it is the polymorphism of the VDR gene and not only the level of the total VDR that is responsible for the sensitivity of human leukemia and lymphoma cells to vitamin D analogues." (PMID 35335121, 2022). "Specifically, the VDR is known to interact with CEBPs to induce leukemia cell differentiation, and indeed the CEBPs are a master regulator in the physiological transcriptional module containing the VDR to regulate monocyte differentiation." (PMID 36558356, 2022). "Using one of the healthy subject’s cDNA sample as a calibrator, we found very similar VDR expression levels in patients with leukemia and healthy individuals." (PMID 32357551, 2020). "The analogs blocked cell cycle in the G0/G1 phase and induced cell differentiation as well as increased VDR level in cytoplasmic fractions of HL-60 or MV4-11 leukemia cell lysates." (PMID 26492238, 2015). "For this study, we have selected THP-1 cells as an attractive leukemia model, as it is the only one for which genome-wide VDR data are available." (PMID 24202443, 2013). "Verbeek also found that the baT genotype contributed to high levels of VDR gene expression in human peripheral blood lymphocytes, leukemia cell line, prostate cell line." (PMID 23825591, 2013).
leukemia (continued). "A similar VDR protein upregulation in leukemia cells was observed when 1,25D was combined with other inducers or enhancers of differentiation, such as all trans retinoic acid (ATRA) and bufalin, a major digoxin-like component of toad venom." (PMID 23259067, 2012). "Notably, VDR was reported to interact with HSP90 in human leukemia cells, indicating a potential role for molecular chaperones in VDR regulation under stress." (PMID 41282147, 2025). "In addition, MYB regulates the nuclear receptor vitamin D receptor (VDR), and 1,25-dihydroxyvitamin D3 (calcitriol) was described as a differentiation inducer in HL-60 and M1 leukemia cells by suppression of MYB." (PMID 38835346, 2024). "We did not observe a significant association of 25(OH)D or VDR levels and overall survival of leukemia patients." (PMID 32357551, 2020). "Thus, we compared plasma 25(OH)D levels and the expression of VDR in peripheral blood mononuclear cells (PBMCs) of yet untreated adult patients with different types of leukemia and matched healthy volunteers." (PMID 32357551, 2020). "Therefore, we decided to analyze the influence of a panel of new analogs on the expression of VDR and MARRS, in terms of both mRNA and protein (in the case of VDR) levels, toward two leukemia cell lines." (PMID 26492238, 2015). "Therefore, because of this intriguing dissociation between phenotypic effects seen in leukemia cells (present studies) and keratinocytes (parallel studies) we have examined the potential binding of 20(OH)D3 to the VDR." (PMID 20360850, 2010). "Therefore, in this first pilot single-center study conducted in Central Kazakhstan, we compared plasma levels of 25(OH)D and the vitamin D receptor (VDR) gene expression levels in peripheral blood mononuclear cells of patients with leukemia and demographically matching healthy volunteers." (PMID 32357551, 2020). "Hence, in vivo, vitamin D may signal through VDR in additional cells in the bone and bone marrow influencing the microenvironment and differentially altering the growth and viability of the leukemia cells." (PMID 32047189, 2020). "Interestingly, vitamin D receptor polymorphism but not its level could be a factor that plays a role in the sensitivity of human leukemia and lymphoma cells to calcitriol and its analog." (PMID 35053549, 2022). "Further studies are needed to elucidate molecular mechanisms involving VDR, RAR and RXR signaling pathways in the induced differentiation of leukemia cells." (PMID 25409436, 2014). "The immortalized cell models, lymphoblastoid and LX2 cells, essentially capture normal VDR signaling, while THP-1 leukemia cells display significant phenotypic responses towards 1,25(OH)2D3 exposure in terms of triggering differentiation." (PMID 24202443, 2013). "In order to test VDR modulation during the differentiative process, we analysed receptor expression in MEG-01 cells, a human megakaryoblastic leukaemia cell line which maintains some characteristics of megakaryocytes." (PMID 20107497, 2010). "Since the CpG region in the promoter of exon 1c in leukemia cell lines was fully methylated, we hypothesized that hypomethylating agents, zebularine (ZEB) or 5-azacytidine (5AZA), may increase VDR expression, and, in consequence, the activity of VDR as a transcription factor." (PMID 32872475, 2020).
hepatocellular carcinoma (29 papers, 2012 to 2026). A malignant tumor that arises from hepatocytes. "Clinical research indicated that genetic variants of the VDR genes were associated with increased susceptibility to HBV-related hepatocellular carcinoma." (PMID 35765066, 2022). "The severity of chronic hepatitis C and susceptibility to hepatocellular carcinoma (HCC) are associated with genetic variations within vitamin D receptor (VDR) in several populations." (PMID 38066559, 2023). "In accordance, previous studies on mouse and human hepatoma cells indicated that the activation of the VDR (Vitamin D Receptor) inhibited the expression of FXR (Farnesoid X Receptor)." (PMID 38412162, 2024). "Studies on mouse and human hepatoma cells also revealed that VDR activation blocked farnesoid X receptor expression, thereby suppressing cholesterol 7α-hydroxylase expression and decreasing cholesterol levels." (PMID 38179303, 2023). "We hypothesized that one or more variants of VDR single nucleotide polymorphisms (SNPs) are associated with hepatocellular carcinoma (HCC) in hepatitis C virus (HCV) cirrhotic patients." (PMID 35996514, 2022). "The diffuse, significant VDR expression we saw in hepatoblastoma samples is correlated in some studies, where significant VDR expression was detected in healthy liver tissue and in hepatocellular carcinoma." (PMID 35884356, 2022). "Calcitriol partially inhibited HCV infection, nitric oxide (NO) release and lipid accumulation in Huh7.5 human hepatoma cells via the activation of vitamin D receptor (VDR)." (PMID 29385741, 2018). "Rats bearing the AH130 hepatoma showed decreased circulating vitamin D compared to control rats, while muscle vitamin D receptor (VDR) mRNA was up-regulated." (PMID 28423519, 2017). "Conversely, the MET induced by the enforced reexpression of the putative tumor suppressor KLF4 in hepatocellular carcinoma cells was accompanied by VDR upregulation and an increase in the inhibitory effect of 1,25(OH)2D3 on cell proliferation." (PMID 26880977, 2016). "However, when directly investigated, norUDCA did not activate mouse PXR or the bile acid sensing nuclear receptors, FXR, or VDR as measured using nuclear receptor-luciferase reporter assays in transfected human hepatoma Huh7 cells." (PMID 36787187, 2023). "As a result, KLF4 and VDR protein expression correlate directly in human hepatocellular carcinoma." (PMID 26880977, 2016). "VDR gene polymorphisms are associated with the presence and severity of NAFLD, as they may influence the regulation of adipose tissue activity, fibrosis, and hepatocellular carcinoma (HCC) development." (PMID 37175993, 2023). "The phenobarbital-treated human hepatoma cell line showed upregulation of CYP24A1 genes, and the dexamethasone-treated osteosarcoma cell line exhibited inhibition of VDR gene transcription." (PMID 37808100, 2023). "Associations between polymorphisms in vitamin D receptor (VDR)/vascular endothelial growth factor (VEGF)/interleukin-18 (IL-18)/mannose-binding lectin (MBL) and susceptibility to hepatocellular carcinoma (HCC) were already explored by many studies, yet the results of these studies were inconsistent." (PMID 31830994, 2019).
viral infection (29 papers, 2009 to 2025). "The relationship between physiology of vitamin D and viral infections is also supported by genetic researches; they evaluated effective variants in the disease susceptibility, which encoding in the VDR gene." (PMID 36411916, 2022). "The association between vitamin D physiologies with viral infections is also confirmed by genetic studies, carried out on genetic variations of vitamin D receptor (VDR) R-encoding disease susceptibility gene." (PMID 36411916, 2022). "The relation between vitamin D physiologies with viral infections is also confirmed by genetic research, carried out on genetic variations of VDR R-encoding disease susceptibility gene." (PMID 36411916, 2022). "We demonstrated that polymorphisms of the VDR gene, in particular TaqI, are associated with viral infections and in particular with viral respiratory tract infections, in infants." (PMID 34226633, 2021). "Among the host genetic factors, polymorphisms in the cytokine promoter gene Vitamin D Receptor and Human Leucocyte Antigen influence the susceptibility to viral infections yet these are individual and population specific." (PMID 33160386, 2020). "Previous studies have suggested that VDR gene polymorphism is related to viral infection 105, and the polymorphism of the VDR gene may influence the effect of VD by affecting its activity and expression." (PMID 38230221, 2024). "Our findings further elucidate genetic susceptibility to viral infections and detection of VDR and VDBP status might help determine high-risk infants." (PMID 34226633, 2021). "In addition, regulation of the vitamin D/VDR axis in the context of other co-factors such as mutation or viral infection may also be important in the etiology of anal cancer, a rapidly growing public health problem with no viable preclinical models." (PMID 27768599, 2016). "Although VDR’s influence spans multiple biological processes, its relationship with viral infections, particularly pseudorabies virus (PRV), remains underexplored." (PMID 39475231, 2024). "Although previous investigations have delved into the relationship between VDR and viral infection, the specific interaction between PRV and VDR remains underexplored." (PMID 39475231, 2024). "When activated, VDR attaches to the VDR element of the cathelicidin promoter region, triggering host defense against viral infections." (PMID 36308699, 2023). "VitD and its receptor VDR have increasingly been recognized for their effects on the regulation of the innate and adaptive immune pathways as well as several bacterial and viral infections." (PMID 37466438, 2023). "Variants in the Vitamin D Receptor (VDR) gene, such as BglI rs739837 and TaqI rs731236, are associated with various viral infection progressions." (PMID 36553614, 2022). "Significant variances were detected between the frequencies of the VDR FokI and VDBP rs7040 alleles and viral infection in the studied groups." (PMID 33801744, 2021). "Considering the incidence of viral infection, significant differences were identified between the frequencies of VDR FokI (OR = 2.035; 95% CI 1.06–2.89, p = 0.030) and VDBP rs7040 (OR = 0.40; 95% CI 0.24–0.67, p < 0.001) T alleles in the studied groups." (PMID 33801744, 2021). "This explains the findings of our study since genetic differences regarding VDR and VDBP were associated with viral infections." (PMID 34226633, 2021). "Further studies will be necessary to identify the factors inhibiting VDR expression following viral infection." (PMID 30326825, 2018). "In contrast, triterpenoid-type compounds (e.g., GPM24, GPM30, GPM32) interacted with a separate subset of targets including ACE, AGTR2, VDR, and were more involved in cardiovascular and renin–angiotensin system-related pathways, as well as metabolic and viral disease modules." (PMID 41471341, 2025). "Different viral infection outcomes also correlate with variations in the VDR gene." (PMID 39272727, 2024).
viral infection (continued). "The roles of mammalian VDR or VitD analogs during different viral infections are controversial." (PMID 37466438, 2023). "and HIV, downregulation of VDR expression is not universally associated with viral infections (34, 38, –, 40)." (PMID 37466438, 2023). "VDR (FokI) and VDBP (rs7040) alleles and their genotype distribution are significantly associated with allograft outcomes including allograft rejection and viral infection in the studied population." (PMID 33801744, 2021). "Our findings suggest that future study of the role of vitamin D in susceptibility to viral infection in infants needs to include also levels of VDBP and vitamin D, in conjunction with the genetic profile of VDBP and VDR, to further understand the role of the vitamin D pathway in viral infections." (PMID 34226633, 2021). "Therefore, the present experiment was intended to evaluate the connection between VDR and VDBP gene polymorphisms with kidney allograft function and outcomes including viral infection and allograft rejection." (PMID 33801744, 2021). "Consensus holds that, in response to viral infection, macrophage vitamin D/VDR signaling initially activates pro-inflammatory pathways (e.g., increased LL37, IL-8), while a more delayed anti-inflammatory response (e.g., decreased IL-8, increased IL-10) serves to limit immune-mediated injury." (PMID 34203190, 2021). "Our Logistic regression analysis showed that the VDR FokI and VDBP rs7040 polymorphisms could significantly increase the Odds ratio of viral infection." (PMID 33801744, 2021). "Since SNPs in the vitamin D receptor (VDR) genes have been associated also with protection from HIV-1 infection, it can be postulated that pro-inflammatory immune responses to viral infection or live viral vaccination are influenced by functional polymorphisms in the VDR gene." (PMID 21933421, 2011). "By targeting components of the VDR-related signaling pathways, we can potentially develop novel therapeutic interventions against PRV and possibly other similar viral infections." (PMID 39475231, 2024). "Virus receptors are known to mediate virus attachment and further lead to virus infection of the host cells, for example, signaling lymphocyte activation molecule (SLAM) and CD6 for measles virus, and vitamin D receptor (VDR) for Hepatitis C virus." (PMID 37358427, 2023). "While there is evidence that vitamin D status can impact the immune response and influence susceptibility to viral infections, the specific role of VDR gene expression differences between genders in viral infections is not well established." (PMID 38474725, 2024). "Research on the relationship between vitamin D and viral infections often focuses on the overall vitamin D status rather than gender-specific VDR gene expression." (PMID 38474725, 2024). "VDR-induced transcription generates LL37 in isolated human airway epithelial cells even in the absence of infection; however, viral infection has a potentiating effect." (PMID 34203190, 2021). "It thus might be a feature more common in viral infections and not entirely HCMV-specific, even though we previously excluded VDR downregulation at least in the context of adenovirus and influenza infection, arguing against a general mechanism." (PMID 36146811, 2022).